MCM2 (minichromosome maintenance complex component 2)
Diseases named in the same sentence as MCM2 in open-access papers (continued):
Sharing a sentence is not in itself a finding about the gene and the disease.
salivary gland carcinoma (1 paper, 2011). A carcinoma that arises from the major or minor salivary glands. "Salivary gland carcinomas express maspin and MCM2 with variable levels and cellular localization, consisting important markers of biological behavior in these tumors." (PMID 21943228, 2011). "The study was conducted to examine the cellular distribution of maspin and MCM2 in salivary gland carcinomas and their value to predict lymph node metastasis." (PMID 21943228, 2011). "All salivary gland carcinomas express maspin and MCM2 with variable cellular localization." (PMID 21943228, 2011). "Maspin and MCM2 are important markers of biological behavior in salivary gland carcinomas." (PMID 21943228, 2011).
sarcoma (1 paper, 2021). A usually aggressive malignant neoplasm of the soft tissue or bone. "In this study, we found that MCM2, 3, 4, and 10 could be used as molecular markers to identify high-risk subgroups of sarcoma patients." (PMID 34239894, 2021). "We found that except for MCM1, all other MCM factors had higher expression levels in sarcoma than in normal tissues (p < 0.05 for MCM2, MCM4, MCM5, MCM6 and MCM7)." (PMID 34239894, 2021). "The present study implied that MCM2–4 and 10 are potential biomarkers for the prognosis of sarcoma." (PMID 34239894, 2021). "The four MCM family members, MCM2, 3, 4, and 10 could be prognostic biomarkers for human sarcoma and a higher expression of these MCM factors predicts poorer outcomes." (PMID 34239894, 2021). "The results showed that high expression of MCM2, MCM3 and MCM4 was significantly related to poor OS of sarcoma patients." (PMID 34239894, 2021). "According to the results, we found that MCM2 and MCM4 were elevated expressed in ONCOMINE and GEPIA datasets with prognostic values, so the key MCM family genes including MCM2 and MCM4 were chosen to be confirmed in sarcoma cell lines." (PMID 34239894, 2021). "MCM2, and MCM4–7 were highly expressed in sarcoma in GEPIA database." (PMID 34239894, 2021). "Therefore, MCM2, MCM3, MCM4, and MCM10 were four potential biomarkers for the prognosis of sarcoma and a higher expression indicates worse outcomes." (PMID 34239894, 2021). "Moreover, high levels of MCM2 and MCM4 mRNA significantly decreased the OS (p < 0.05) of sarcoma patients." (PMID 34239894, 2021). "So MCM2, MCM3, and MCM4 seemed to be three potential biomarkers for the prognosis of sarcoma." (PMID 34239894, 2021). "Furthermore, we analyzed the prognostic value of MCMs for sarcoma in GEPIA and found that MCM2, MCM3, MCM4, and MCM10 are prognostic biomarkers for human sarcoma." (PMID 34239894, 2021).
serous ovarian cancer (1 paper, 2021). "The serous ovarian cancer dataset indicated that the percentages of DNA alterations of MCMs were 5% (MCM2), 4% (MCM3), 5% (MCM4), 2.6% (MCM5), 1.2% (MCM6), and 5% (MCM7)." (PMID 34178669, 2021).
Shwachman-Bodian-Diamond Syndrome (1 paper, 2023). "In particular, MCM2 (minichromosome maintenance complex 2), MCM5, MCM7, multiple copies in T-cell lymphoma-1, RPS25 ribosomal protein S25, and Shwachman-Bodian-Diamond Syndrome were successfully confirmed." (PMID 37391046, 2023).
skin cancer (1 paper, 2020). "Accordingly, an abnormal level of MCM2 has been reported widely to associate with human cancers, including breast, colon, gastric, rectal, and skin cancer development." (PMID 32469983, 2020).
Stroke (1 paper, 2023). Sudden impairment of blood flow to a part of the brain due to occlusion or rupture of an artery to the brain. "Two weeks after stroke induction, significant changes in the proliferation behavior of the MCM2+ cells were observed after standard housing." (PMID 36831319, 2023).
synovial sarcoma (1 paper, 2024). "Investigations into the molecular mechanisms underpinning FAM83D’s regulation of STAT1, BIRC5, MCM2, as well as CDK1 in synovial sarcoma, are currently underway in our laboratory." (PMID 38512482, 2024). "Collectively, these results point to a potential involvement for FAM83D in the development of synovial sarcoma could be mediated via the regulation of STAT1, BIRC5, MCM2, as well as CDK1." (PMID 38512482, 2024).
tongue cancer (1 paper, 2021). A malignant neoplasm affecting the tongue. "The levels of MCM2 mRNA were significantly elevated in tongue cancer compared to normal controls." (PMID 34440557, 2021).
tongue SCC (1 paper, 2008). "Quantitative real-time PCR analysis showed that MCM2 mRNA expression is significantly higher in tongue SCC than in epithelia dysplasia." (PMID 19116018, 2008). "In other words, MCM2 and CDC45 had a higher accuracy than CDC6 and CDT1 for distinguishing precancerous stages from malignant tongue SCC." (PMID 19116018, 2008). "The area under the ROC curve (AUC) was 0.679 for CDC6 (p = 0.032), 0.808 for CDT1 (p = 0.000), 0.933 for MCM2 (p = 0.000) and 0.836 for CDC45 (p = 0.000), indicating that MCM2 and CDC45 were superior to CDC6 and CDT1, and could be used as useful tumor markers in diagnosing tongue SCC." (PMID 19116018, 2008).
urothelial carcinoma (1 paper, 2012). A malignant neoplasm derived from the transitional epithelium of the urinary tract (urinary bladder, ureter, urethra, or renal pelvis). "Moreover, MCM-2 has been studied in a wide range of human malignancies and has been associated with tumor histopathological grade in several malignancies, including colon, oral cavity, ovarian and urothelial carcinoma." (PMID 22493662, 2012).
uterine corpus leiomyosarcoma (1 paper, 2021). "Quade Uterus datasets showed that MCM2 was overexpressed in uterine corpus leiomyosarcoma with a fold change of 26.250." (PMID 34239894, 2021).
viral hepatitis (1 paper, 2015). An acute or chronic inflammation of the liver parenchyma caused by viruses. "In NAFLD and ALD, the frequency of hepatocyte p21 expression was much higher than hepatocyte Mcm-2 expression; in viral hepatitis hepatocyte p21 and Mcm-2 expression were similar." (PMID 26024529, 2015).
tumor (188 papers, 2004 to 2026). "MCM2 is a well-recognized group of proteins that can cause tumor initiation, proliferation, and progression by modulating the cell cycle and DNA replication stress." (PMID 39001449, 2024). "In lung cancer, omics data of MCM2 overexpression is analyzed using the Gene Expression Omnibus database, which is associated with large tumor size, different malign degrees, and clinical stages." (PMID 36776764, 2023). "In summary, our findings indicate that impaired histone inheritance evoked by MCM2-2A mutation promotes tumor growth and invasion by facilitating the emergence of distinct subclones." (PMID 37301892, 2023). "In this study, we constructed a tumor model of impaired inheritance of parental histones by introducing an MCM2 histone-binding domain (HBD) mutation in the breast cancer cell lines." (PMID 37301892, 2023). "MCM2 was significantly overexpressed in almost all human cancers/subtypes in TCGA and was associated with tumor mutation burden, tumor stage, immune therapy response, immune infiltration, and poor patient prognosis." (PMID 36499305, 2022). "Gene mutation of MCM2 was associated with the tumor status, lymph node status, metastatic status, pathologic stage, histologic grade, and prognosis for ESCC patients." (PMID 36465369, 2022). "Various computational tools were used to investigate the MCM2 expression level, genetic mutation rate, and regulating mechanism, immune infiltration, tumor diagnosis and prognosis, therapeutic response and drug sensitivity of various cancers." (PMID 35693940, 2022). "Expression of MCM2 was significantly correlated with tumor-associated macrophages (TAMs), Th17 cells, and regulatory T cells (Tregs)." (PMID 36445337, 2022). "Higher expression of MCM2 or NUP37 was significantly associated with advanced tumor stage and worse overall survival in 3 large independent HCC cohorts (n = 820)." (PMID 35093119, 2022). "Expression of MCM2 was significantly associated with the clinical characteristics (e.g., T stage and tumor stage) of patients with SKCM." (PMID 34490114, 2021). "Using mouse NB cisplatin-treated xenografts, we identified two genes within the list associated to the malignant stage (MCM2 and carbonic anhydrase 9), whose expression is positively correlated with tumor growth." (PMID 33153038, 2020). "The frequency of Ki-67, MCM2, geminin, and aurora A and B was significantly associated with tumor grade and ploidy status in epithelial ovarian carcinomas." (PMID 29963273, 2018). "Highly malignant tumors overexpress the minichromosome maintenance 2 (MCM2) protein in the nucleus, which is associated with advanced tumor grade, advanced stage, and poor prognosis." (PMID 29963273, 2018). "In the present study we use micronuclear DNA sequences to show that the region of Chr10 carrying the Tcf3 gene is also the site of elevated ongoing genome instability even prior to tumor initiation in MCM2 deficient mice on the 129Sv genetic background." (PMID 28045896, 2017). "Highly malignant tumors express high levels of the minichromosome maintenance 2 (MCM2) protein, which is associated with advanced tumor grade, advanced stage, and poor prognosis." (PMID 26430873, 2015). "A high level of MCM2 expression in malignant tumors is associated with several clinicopathological parameters such as advanced tumor grade, advanced stage, and poor prognosis." (PMID 26430873, 2015). "Expression levels of Mcm2, geminin, Plk1, Aurora A and H3S10ph were strongly associated with tumour grade." (PMID 19240714, 2009). "Increasing grade of tumour was associated with significantly increased expression of Ki67, Mcm2 and geminin, and lower expression of the differentiation markers ER and PR (Jonkheere-Terpstra test, P<0.001 in each case)." (PMID 16278669, 2005). "Hub genes CENPU and MCM2 are expected to be new tumor diagnostic markers and therapeutic targets." (PMID 37723560, 2023).
tumor (continued). "Since DNA replication stress frequently occurs in MCM2 deficient cells, it is meaningful to explore whether targeting MCM2 can inhibit proliferation and stimulate anti-tumor immunity simultaneously." (PMID 36303105, 2022). "MCM2 was significantly upregulated in almost all cancers and cancer subtypes in The Cancer Genome Atlas and was closely associated with tumor mutation burden, tumor stage, and immune therapy response." (PMID 35693940, 2022). "Since DNA replication stress, which may stimulate anti-tumor immunity, frequently occurs in MCM2 deficient cells, it also proposes the possibility that MCM2 targeting improves the effect of tumor immunotherapy." (PMID 36303105, 2022). "Meanwhile, the expression levels of MCM2/4/6/7/8 were associated with advanced tumor stages." (PMID 33936158, 2021). "Moreover, the protein and mRNA levels of Pbk, Mcm2, Cyclin B2, Cyclin D2 and Cyclin A were markedly increased in menin-deficient tumours and dramatically rescued to normal levels by β-catenin ablation in mice." (PMID 25517963, 2014). "Genetic background has also been reported to influence tumor latency in MCM2-deficient mice." (PMID 20838603, 2010). "Here we tested enrofloxacin, a Minichromosomal Maintenance Complex Component (MCM2) inhibitor, for its ability to increase tumor cell sensitivity to platinum-based drugs, thus suggesting a potential synergistic therapeutic strategy." (PMID 42041882, 2026). "IHC staining of tumor tissues acquired on the day of sacrifice showed decreased MCM2, MCM5, BrdU and MKI67 levels in TRIM21 knockdown groups, contrasting with elevated TCF3 levels." (PMID 40998798, 2025). "Correspondingly, we confirmed lower MCM2 expression levels in murine models treated with combined therapy compared to controls, in both primary and metastatic tumour lesions." (PMID 41020311, 2025). "C1GALT1 was upregulated in several GI and GU cancers, correlating with poor survival and elevated expression of proliferation markers like MKI67, PCNA, and MCM2–7, suggesting a role in tumor growth." (PMID 40548474, 2025). "In contrast, nuclear YAP (rs = 0.263, p ≤ 0.01) and TAZ (rs = 0.527, p ≤ 0.001), MCM2 (rs = 0.444, p ≤ 0.001), and Ki-67 stains (rs = 0.427, p ≤ 0.001) positively correlated with tumor grading." (PMID 39859373, 2025). "ANXA3 KD was successfully achieved in tumour-derived primary cells, resulting in a reduction of the expression of the proliferation marker MCM2 and significantly reducing proliferation as measured by the EdU assay." (PMID 40562609, 2025). "Mechanistically, RNA sequencing revealed that the combination therapy blocked MCM2‐mediated DNA replication in TNBC cells, causing G1/S phase arrest and enhancing tumour suppression." (PMID 41020311, 2025). "In addition, we found that the expression of RUNX1, CDC20 and MCM2 correlated with the infiltration of tumor immune cells through bioinformatics analysis, and their expression may cause the tumor immune cells to be exhausted, and the possible mechanism of action remains to be investigated." (PMID 38886545, 2024). "MCM2 and MCM7, defined as CRC-related genes, were overexpressed and associated with proliferative capacity, tumor histological grade, lymph node metastasis and vascular invasion in CRC." (PMID 39520627, 2024). "MCM2 is overexpressed at the luminal surface in BE, and its expression correlates with the degree of dysplasia and the tumor grades." (PMID 39001449, 2024). "We conducted a pan-cancer analysis to investigate the immune effects of L1 ASP associated genes, specifically MCM2 and CENPU, in the tumor immune microenvironment." (PMID 37723560, 2023). "The MCM2 protein is overexpressed in the nucleus of high malignant tumors, which is related to the late stage, late stage and poor prognosis of the tumor." (PMID 37480569, 2023). "MCM2 protein positivity is thought to be a more accurate indicator of tumour prognosis inOSCC compared to Ki-67." (PMID 38415027, 2023).
tumor (continued). "Compared toKi-67, MCM2 protein positivity is regarded to be a more reliable measure of the prognosis of the tumour in OSCC." (PMID 38415027, 2023). "Thyroid tissues were immunohistochemically stained for different tumor proliferative markers: Minichromosome maintenance proteins 2 (MCM2), Ki-67 labeling index, E-Cadherin, Neuropilin-1 and Metallothionein." (PMID 36676734, 2023). "Conversely, upregulation of E2F targets (e.g., PRDX4, MCM2; FDR = 2.6e-24) and extracellular matrix genes (e.g., COCH, MATN3; FDR = 8.0e-18) were strongly associated with tumor growth and resistance to ICI-4W." (PMID 37433281, 2023). "Through protein interaction network analysis, we discovered two hub genes, CENPU and MCM2, that play important roles in pan-cancer species and are closely related to tumor T staging and tumor stemness in pan-cancer." (PMID 37723560, 2023). "On the other hand, MCM2 regulates DNA replication, and its overexpression was detected in several human tumors where the dysfunctional MCM2 was correlated with tumor invasion and poor patient survival." (PMID 37626750, 2023). "Higher expression of MCM2 and MCM3 was found to correlate with disease recurrence and both proteins were found to be independent prognostic risk factors for tumor free- and overall- survival." (PMID 37197427, 2023). "The results indicated that HBV infection upregulated MCM2/5 expression through enhanced YTHDF2 O-GlcNAcylation to accelerate tumor formation, whereas OSMI-1 treatment or pSECC-sgYthdf2 exhibited the opposite effect." (PMID 36765030, 2023). "Subgroup U-II was more related to tumor proliferation, including cell cycle (MCM2, ANAPC4, CHEK1, etc.), RNA splicing, and DNA repair." (PMID 35659036, 2022). "Meanwhile, correlation analyses of MCM2 or NUP37 expression with clinicopathological features revealed a significant association between NUP37 overexpression and tumor metastasis." (PMID 35093119, 2022). "Increased level of MCM2 accelerated proliferation, migration, and invasion of tumor cells, and inhibited apoptosis." (PMID 36303105, 2022). "It is possible that targeting MCM2 makes cold tumors to be hot and enhances sensitivity of tumor immunotherapy." (PMID 36303105, 2022). "Forty cases of each tumor were immuostained with ki67, MCM2, and geminin followed by assessment of labeling indices (LIs)." (PMID 32972865, 2022). "Combined with doxorubicin, Hph-1-gp70 enhanced cell apoptosis and showed anti-tumor efficacy in cells with high MCM2 expression." (PMID 36303105, 2022). "For BRCA, phosphorylation of S27, S41 and S139 in MCM2 was significantly higher in tumor tissue (all p < 0.05)." (PMID 35693940, 2022). "Bioinformatic analysis revealed that the expression of MCM2 was upregulated in LUAD and LUSC, and associated with the tumor stage." (PMID 36303105, 2022). "The results demonstrated that higher tumor (T) stage was correlated with only MCM2 overexpression; (p = 0.02)." (PMID 34144903, 2022). "IHC staining unveiled that overexpression of HAR1A reduced tumor cell proliferation, as shown by decreased MCM2 and PCNA positive tumor cells in lenti-HAR1A cell-derived tumors." (PMID 35740511, 2022). "Both proliferative tumor cells and quiescent CSCs should be taken into account when predicting chemotherapy response with the expression of MCM2." (PMID 36303105, 2022). "Western blot showed that the protein expression of CDC7 and MCM2(pSer53) were down-regulated in tumor sample treated by dequalinium." (PMID 36426371, 2022). "MCM2 has been identified as a new biomarker for predicting tumor cell proliferation and prognosis of various cancers." (PMID 35093119, 2022). "The anti-tumor effect induced by MCM2 inhibition implies the potential of MCM2 to be a novel therapeutic target for cancer treatment." (PMID 36303105, 2022). "MCM2 was proved as a reliable marker for assessing tumor growth, aggressiveness, and prognosis in ESCC patients." (PMID 35711839, 2022).